RNU6-310P (RNA, U6 small nuclear 310, pseudogene)
Gene: Small nuclear RNA gene on chromosome 4 (53,265,461 to 53,265,567, reverse strand). Ensembl gene ENSG00000207385.
Homologues: Orthologues: chimpanzee U6 (100% identical), macaque U6 (97% identical), pig U6 (91% identical), dog U6 (88% identical), mouse Gm24198 (80% identical), rat LOC120095375 (71% identical). Paralogues in human: RNU6-211P (93% identical), RNU6-116P (93% identical), RNU6-20P (93% identical), RNU6-35P (93% identical), RNU6-1145P (92% identical), RNU6-1152P (92% identical), RNU6-1289P (92% identical), RNU6-1316P (92% identical), RNU6-15P (92% identical), RNU6-25P (92% identical), RNU6-393P (92% identical), RNU6-41P (92% identical), and 1287 more.